AXL (AXL receptor tyrosine kinase)
Diseases named in the same sentence as AXL in open-access papers (continued):
Sharing a sentence is not in itself a finding about the gene and the disease.
melanoma (continued). "Regarding melanoma motility, AR was previously reported to promote melanoma metastasis via transcriptional upregulation of miRNA-539-3p, which impacts MITF and AXL signaling." (PMID 38326303, 2024). "Although melanoma can be classified into MITF-low/AXL-high or MITF-high/AXL-low melanoma at the tumor level, subclones with AXL-high and MITF-high expression co-exist in melanoma at the single cell level." (PMID 37239381, 2023). "In order to evaluate the phenotypic diversity of our samples, we mapped the expression profile of key melanoma cell-state regulatory genes such as the NGFR, RXRG, MITF, SOX10, SOX9 and AXL genes." (PMID 36765773, 2023). "For example, the expression of AXL, EGFR and NGFR, which are related to cell dedifferentiation and plasticity, is significantly higher in melanoma after drug treatment." (PMID 37483492, 2023). "First, we showed that JI130 and MEL56 inhibit cell migration in two invasive melanoma cell lines (MM029 and MM165) and downregulate the mRNA expression of the main EMT/invasion markers such as AXL, EGFR, MET, ZEB1, WNT5A, TGFβ, SNAI1, TWIST and MMPs." (PMID 37508519, 2023). "In single-cell analysis of human melanomas, a subpopulation of cells expressing high levels of AXL, a putative cancer stem cell marker, and low levels of MITF were present in treatment-naive human melanoma samples." (PMID 37021774, 2023). "These AXL-high MITF-low cells were admixed with AXL-low MITF-high differentiated cells, demonstrating cellular heterogeneity present in untreated melanomas." (PMID 37021774, 2023). "AXL overexpression in melanoma cells reduced the expression of MER and decreased metastatic colonies with unchanged WNT5A, implying that AXL is downstream of WNT5A." (PMID 36646673, 2023). "Of more concern is the elevated AXL expression and the reduced expression of MHC class I molecules in the melanoma immunotherapy-resistant phenotype." (PMID 37265798, 2023). "Co-treatment with a MEK inhibitor and an AXL inhibitor were synergistic in cell lines and xenograft models of TNBC, and a triplet including a BRAF inhibitor was also synergistic in melanoma models." (PMID 36358725, 2022). "A recent study has reported similar results using a new selective AXL/FLT3 inhibitor, SKI-G-801 in B16F10 melanoma, CT26 colon, and 4T1 BCa models." (PMID 35572601, 2022). "The phenotype switching in melanoma is marked with downregulation of MITF and upregulation of RTKs, such as AXL and EGFR." (PMID 35406721, 2022). "In YAP1-activated melanoma cells, SLC35B2 knockout abrogated HS surface expression and limited activity of YAP1-stimulated RTKs including ERBB3, EGFR, and AXL." (PMID 35798875, 2022). "We next examined the levels of DDR1 and DDR2 in a collection of melanoma cell lines and short‐term melanoma cultures in relation to the cell state differentiation markers MITF, SOX10, and AXL." (PMID 34957688, 2022). "Several reports identified an inverse correlation between transcript levels of AXL and the transcription factor MITF in a melanoma subset characterized by marked resistance to MAPKis." (PMID 35798875, 2022). "AXL and/or GAS6 overexpression have been reported in multiple human cancers such as glioma, melanoma, breast, lung, and ovarian cancer, and high level of AXL was associated with increased tumor progression and poorer overall survival." (PMID 35622156, 2022). "During acquired resistance to BRAF inhibition, the high expression of AXL, a member of TAM, is a marker of melanoma dedifferentiation, indicating these are vulnerable to ferroptosis inducers." (PMID 35399527, 2022). "An impact of HS levels on the activity of multiple RTKs including ERBB, FGFR, and PDGFR family members as well as AXL and MET in tumor types apart from melanoma has been described." (PMID 35798875, 2022).
melanoma (continued). "The molecular link between AXL and MHC I expression previously identified by Aguilera and colleagues in murine models was highlighted in a recent study analyzing 94 melanoma tumors collected at baseline and PD-1 inhibitor progression." (PMID 35572601, 2022). "Another strategy that melanoma cells use to adapt to drug-induced stress is by upregulating autophagy, a result of ER stress and TAM receptor protein tyrosine kinases (TYRO3, AXL, MER) pathway activation." (PMID 33922284, 2021). "For example, enapotamab vedotin (AXL-107-MMAE), was designed to specifically target the AXLhigh dedifferentiated melanoma cells." (PMID 34604096, 2021). "During treatment, when melanoma cells bypass BRAF inhibition, MITF expression inversely correlates with AXL, a TKRs family member." (PMID 33922284, 2021). "Within the metastatic melanoma samples, there was a clear difference in the expression of lipid metabolism-related genes based on MITF/AXL status." (PMID 37849907, 2021). "EMT-like phenotype switching is important for metastatic melanoma progression, and it is orchestrated by MITF, AXL, and EMT-inducing transcription factors (EMT-TFs), such as TWIST, ZEB, and SLUG." (PMID 35008286, 2021). "We examined TNFα effects on melanoma differentiation by analyzing the accumulation of the key marker proteins MITF, Melan A, AXL and NGFR in the 40 melanoma cell lines." (PMID 34073253, 2021). "In melanoma cells, targeted therapy induced AXL expression, and co-treatment of AXL-expressing cells with an antibody–drug conjugate and MAPK inhibitors synergistically prevented tumor growth in melanoma patient-derived xenografts." (PMID 34071428, 2021). "Targeting mesenchymal‐like cells using an antibody‐drug conjugate, AXL‐107‐MMAE, showed promising effects in a preclinical model of melanoma." (PMID 33724679, 2021). "In response to ERK and MEK inhibition, AXL/MITF-mediated drug resistance is observed among mutant BRAF and NRAS melanoma cell lines." (PMID 32245042, 2020). "TGFß exposure promoted variable levels of de-differentiation markers N-cadherin, AXL and SNAIL, with all three melanoma cell lines tested showing TGF-ß mediated induction of at least one of these markers." (PMID 32312968, 2020). "A different mechanism enabling survival of both melanoma and NSCLC cells in the presence of targeted therapy involves upregulation of the RTK AXL and the subsequent induction of an epithelial-to-mesenchymal transition (EMT)." (PMID 33291749, 2020). "Western blots showed that primary melanoma cells express lower levels of SOX2, GLI1, ST3GAL1, and AXL than metastatic melanoma cells, and that the latters harbor a stronger activation of SOX2/GLI1-ST3GAL1-AXL axis." (PMID 33203881, 2020). "AXL, another HSP90-interacting protein relevant for melanoma, has been identified as a driver of resistance to targeted drugs in melanoma, and a regulator of metastasis-promoting phenotype of melanoma cells." (PMID 31659567, 2020). "The mesenchymal phenotype was also shown to be accompanied by AXL up-regulation both in NSCLC and in melanoma DTPs16." (PMID 32595946, 2020). "PLX4032 has been also reported to modify MITF activity and expression in certain melanomas, including the highly invasive BRAFV600E mutant COLO829 melanoma line, resulting in a MITF-High/AXL-Low phenotype." (PMID 33202765, 2020). "A significant proportion of established human melanoma cell lines express IL32, with its expression being highly correlated with a dedifferentiation genetic signature (high AXL/low MITF)." (PMID 30953519, 2019). "We also observed a correlation between IL32 expression, derived from tumor cells and the surrounding microenvironment, and a high AXL/low MITF gene signature, as in the melanoma cell lines." (PMID 30953519, 2019). "We observed a correlation between IL32 expression in melanoma tumor biopsies with a high AXL/low MITF drug-resistant signature, consistent with data from melanoma cell lines." (PMID 30953519, 2019).
melanoma (continued). "By western blot analysis in 12 melanoma cell lines we tested expression of NFATc2, of several EMT-related proteins as well as of AXL and MITF, the prototypic markers of the alternative invasive/proliferative transcriptional programs of melanoma." (PMID 30710146, 2019). "(A-B) Scatterplot of log2 FPKM expression values between IL32 and select immune genes (A) or between the ratio of AXL and MITF log2 FPKM expression values (B) in the melanoma TCGA dataset (n = 479)." (PMID 30953519, 2019). "NFATc2 showed a positive correlation with AXL, SNAI1, CDH2, and ZEB1 even in the TCGA melanoma dataset." (PMID 30710146, 2019). "Opposing AXL/MITF expression in melanoma subsets has gained recent interest, because MITF-low/AXL-high expression signatures were found in tumors of a subgroup of melanoma patients resistant to BRAF/MEK inhibitor treatment." (PMID 29614062, 2018). "These and other studies indicate the presence of a third subpopulation in melanoma that expresses MITF, AXL, and WNT5A simultaneously." (PMID 29881716, 2018). "These include two different mouse monoclonal antibodies raised against the extracellular domain of human TYRO3 that block GAS6-induced TYRO3 signaling in melanoma cells and have low cross-reactivity with MERTK and AXL." (PMID 30501104, 2018). "The three melanoma short-term cultures show common themes of PT dynamics such as a stromal signature at initiation, bipolar expression of the MITF/AXL signature and opposing regulation of poised and activated promoters." (PMID 29614062, 2018). "These patterns appear to be relatively common mechanism involved in melanoma progression but with slight modifications, e.g., for MITF/AXL expression and oxphos." (PMID 29614062, 2018). "In the present analysis, NRAS-mutant cells activated the AXL program and BRAF/NRAS wild type cells the MITF program which also resembles the melanoma pigmentation subtype described earlier." (PMID 27903987, 2017). "A recent study of single cell malignant melanoma transcriptomes has further refined these signatures and defined two main transcriptional states of melanoma cells: the MITF and AXL gene programs." (PMID 28060736, 2017). "To identify a representative cell line, we assessed the AXL and MITF expression status in a panel of melanoma cell lines and their link to response to BRAF inhibition." (PMID 28606996, 2017). "Thus, the neural crest origin, but de‐differentiated nature of AXL‐high melanoma cells might explain why they express preferentially EDNRA, while differentiation towards the melanocyte lineage, triggered by MITF expression, results in a switch to EDNRB expression." (PMID 28606996, 2017). "AXL, a known target of FRA1 that promotes EMT in epithelial cells, exhibit high levels of expression in our resistant melanoma models." (PMID 27596438, 2016). "This conclusion is based on: 1) the down regulation of AXL, EGFR, IGF-1R and PDGFRβ in ShRUNX2 knocked down melanoma cell lines or RUNX2-specific U1 Adaptors-transfected melanoma cells." (PMID 27102439, 2016). "Up-regulation of the expression of EGF-R, PDGFRβ, AXL and IGF-1R in melanoma cells that have developed resistance to BRAF V600E targeted therapy results in reactivation of the MAPK and the PI3K/AKT pathways." (PMID 27102439, 2016). "1205LU melanoma cells exhibited reduced levels of RUNX2 expression at the two time points and a parallel decrease in EGFR and AXL expression." (PMID 27102439, 2016). "Multiple RTKs can be co-expressed in resistant melanoma cells, with expression clusters involving EGFR, ERBB3, AXL and PDGFR being identified leading to multiple resistance drivers that are difficult to target with single drugs." (PMID 26426052, 2015). "Since the overexpression of genes such as AXL and FOSL1 plays an important role in resistance to traditional therapies in melanoma and other types of tumors, part of the scientific research has focused on the regulatory mechanisms activated upstream by non-coding RNAs." (PMID 40869968, 2025).
melanoma (continued). "Notably, melanoma dedifferentiation marker NGFR and drug resistance marker AXL were upregulated in the tumor cell cycle G2/M program, suggesting potential interactions with mregDC that remain to be elucidated." (PMID 40890106, 2025). "As to the close relation of the AXL and FRA1 proteins with the invasion, migration, and proliferation in melanoma cell lines, we investigate whether these genes could be targeted by miR-20a-3p and/or miR-34a-5p." (PMID 40869968, 2025). "MITF levels are higher in melanocytes than melanoma cells, inversely correlated with AXL and FSCN1, but FRA1 modulation did not alter MITF levels, consistent with RNA-seq and Cut&Run data showing no direct FRA1 regulation of MITF." (PMID 41286309, 2025). "Moreover, silencing AXL, CDK6, or FSCN1 significantly reversed the stimulation of melanoma cell invasion by FRA1." (PMID 41286309, 2025). "This analysis suggests several classes of drugs such as glucocorticoid receptor (NR3C1) agonists, AXL inhibitors, PARP1 inhibitors and HDAC inhibitors as the most consistently expressed candidate drug-treatments in invasive melanoma across all studies examined." (PMID 38183207, 2025). "For instance, Lornoxicam (a selective COX-2 inhibitor), Aspirin, and Acetaminophen can inhibit melanoma metastasis and recurrence by inhibiting the formation of the Hsp90-CDC37 complex, leading to the misfolding of AXL, thus initiating the ubiquitination–proteasome system (UPS) to degrade AXL." (PMID 39598398, 2024). "mIF did not reveal any correlation between the proportion of AXL or MITF melanoma cell phenotypes and the density of leukocyte infiltration, as identified by CD45 expression (not shown)." (PMID 39697983, 2024). "To this aim, we exposed LOX IMVI sensitive melanoma cells to increasing concentrations of a BRAFi for two months and at each step of drug increase we collected total RNAs from samples to evaluate the levels of mir-579-3p, MITF, TYR, and AXL by qRT-PCR." (PMID 38472212, 2024). "Notably, four clinical trials on myeloma, diffuse large B cell lymphoma (DLBCL), melanoma, and NSCLC are ongoing which combine anti-PD1 antibody and IL-17A (NCT03111992), CD22 (NCT03287817), KIT (NCT04493203), or AXL (NCT04681131), respectively." (PMID 38349411, 2024). "The same study also showed that resistant melanomas possess low MITF expression, but high levels of inflammatory nuclear factor ‘kappa-light-chain-enhancer’ of activated B-cells (NF-ĸB) signaling and the receptor tyrosine kinase (RTK) AXL." (PMID 36675114, 2023). "Elevated expression of AXL also reduces tumor sensitivity to both chemotherapy and poly ADP ribose polymerase (PARP) inhibition, and confers resistance to cisplatin in melanoma cells and in ovarian cancer cells." (PMID 37370757, 2023). "Similarly, in a study on the heterogeneity of melanoma cell lines and tumors, AR expression was found to cluster together with EGFR and SERPINE1 in an undifferentiated AXL positive subgroup connected with targeted drug resistance." (PMID 37838724, 2023). "The TCGA melanoma cohort was sub-grouped into well-differentiated and poorly differentiated tumors based on expression of the differentiation drivers microphthalmia transcription factor (MIFT) and AXL, a member of the TAM family of receptor tyrosine kinases." (PMID 37259155, 2023). "The expression of AXL is inversely related to that of MITF, so that MITFhigh/AXLlow (proliferative) and MITFlow/AXLhigh (invasive) populations contribute mostly to intratumor heterogeneity in melanoma and, thereby, resistance to therapy." (PMID 37898636, 2023). "AR expression also positively correlated with SERPINE1 and AXL levels in the metastatic but not primary lesions, in keeping with the complex role played by these genes in melanoma progression." (PMID 37838724, 2023).
melanoma (continued). "In conclusion, our findings have shown that the AXL inhibitor BGB324 affects multiple cellular pathway and cell death mechanisms and represents an attractive approach for improving standard targeted treatment in malignant melanoma." (PMID 35332208, 2022). "Thus, in aggressive melanoma tumors with acquired resistance, MITF and AXL levels correlate inversely." (PMID 35956175, 2022). "In adults, AXL expression is relatively low, but aberrant Gas6/AXL expression has been detected in a number of human malignancies, including breast cancer, chronic lymphocytic leukemia (CLL), lung cancer, pancreatic cancer, glioblastoma, melanoma." (PMID 34926461, 2021). "Consequently, at the acquired resistance and relapse stage, melanomas show a predominant expression of AXL and NGFR, along with an overall trend towards an AXL/AP-1/TEAD-driven gene signature." (PMID 34604096, 2021). "Moreover, the tyrosine kinase receptor AXL was identified as a ST3GAL1 substrate, which is fundamental for the pro-invasive effects of ST3GAL1 in melanoma cells." (PMID 34440905, 2021). "In melanoma, MAPK inhibition has been shown to be less effective against cells with high expression of stem-like markers such as nerve growth factor receptor (NGFR, also known as CD271), JARID1B or AXL." (PMID 33800547, 2021). "In fact, AXL was induced (fold change > 1.5) in only 4/14 (29%; SCC14-0257, HT144, MelAT, D24M) while NGFR was induced (fold change > 1.5) in 4/14 (29%; NM16, MM200, HT144, D22) dedifferentiated melanoma cell lines." (PMID 34073253, 2021). "The majority of melanoma cell lines (23/40: 15/31 cutaneous, 8/9 uveal) showed features of the melanocytic state, including the high expression of MITF and Melan A along with low levels of AXL and/or NGFR." (PMID 34073253, 2021). "Another 14/40 melanoma cell lines (13/31 cutaneous and 1/9 uveal) displayed the neural crest-like dedifferentiated subtype with low MITF and Melan A, and elevated, albeit variable levels, of AXL and/or NGFR." (PMID 34073253, 2021). "In contrast, AXL inhibition in BRAF mutant melanoma may be more effective in PTEN wild-type patients, as phosphorylated AXL is only significantly increased in BRAF inhibitor-resistant cell lines in the context of endogenous PTEN." (PMID 33105713, 2020). "In this study, we profile the expression of MER, TYRO3, and AXL among multiple human cancer cells, and assess induction of phosphorylated AKT (pAKT) by GAS6 and reversal by AXL/MER inhibitors in human melanoma G361 cells that were found to express high levels of MER and TYRO3, but not AXL." (PMID 32042425, 2020). "As in the case of AXL-positive cells in untreated melanomas, pre-existing subpopulations can emerge through non-genetic Darwinian selection because of particular intrinsic properties that favor growth in the presence of the drug." (PMID 33291749, 2020). "Finally, the AM404 + GSK126 combination, after O/N treatment, reversed the EMT-like profile of melanoma cells by reducing SNAIL, ZEB1, AXL, and α-catulin protein expression while upregulating MITF and E-cadherin." (PMID 30710146, 2019). "In the TCGA melanoma dataset, the top 312 genes with a positive correlation (down to Spearman r = 0.5) with the prototypic EMT marker ZEB1, were also positively correlated with SNAI1, NFATc2, CDH2, and AXL, but negatively with MITF and CDH1." (PMID 30710146, 2019). "Nevertheless, we were able to obtain reproducible up‐regulation of genes including EGR1, TXNIP, AXL, CYR61, LIMS2 and TNFRSF12A in MDA‐MB‐435s and MV3 melanoma cell lines and significant increase in protein levels as well, suggesting potential implication in other melanoma cells." (PMID 31044520, 2019). "Melanomas of a “MITF‐high” phenotype usually respond well to BRAF inhibitor therapy, but these melanomas also contain subpopulations of the de novo resistance “AXL‐high” phenotype." (PMID 28606996, 2017).